SDC1 (syndecan 1)
Diseases named in the same sentence as SDC1 in open-access papers (continued):
Sharing a sentence is not in itself a finding about the gene and the disease.
colon carcinoma (26 papers, 2008 to 2025). "Two epithelial-derived colon cancer cell lines expressing SDC1 and CASP4 were also susceptible to SCGB3A2-LPS treatment." (PMID 33452234, 2021). "At the molecular level, our data point at an upregulation of several components of the notch signaling pathway, which we previously linked to Sdc-1 function in breast and colon cancer." (PMID 33102470, 2020). "To summarize, we have shown for the first time the involvement of HPSE in colon cancer stem cell properties and observed an increase in cell invasiveness linked to the regulatory interplay of Sdc-1 and HPSE." (PMID 32477959, 2020). "Although the precise mechanisms underlying this association are not fully understood, loss of Sdc1 emerges as an indicator of augmented colon tumor progression in the setting of chronic inflammation." (PMID 28350804, 2017). "Altogether these results suggest that Sdc1 loss promotes colonic tumor growth through augmented intestinal inflammation, activation of IL6-STAT3 signaling axis, and subsequent induction of Cyclin D1 and other pro-cancerous effectors." (PMID 28350804, 2017). "Previous immunohistochemical studies performed with syndecans in colon cancer have demonstrated a loss of expression of syndecan-1 in CRCs, some of which have been found to correlate with tumor stage and metastasis." (PMID 26482785, 2015). "In colon cancer, the stromal cell expressed SDC1 was associated with good prognosis." (PMID 41364407, 2025). "Shed syndecans have been demonstrated to be plausible biomarkers for predicting cancer progression in some studies, namely elevated serum levels of syndecan-1 are associated with a poor prognosis in bladder cancer, cervical cancer, and colon cancer, among others." (PMID 36016277, 2022). "Based on the deregulated expression of Sdc-1 and HPSE in colon cancer and the role of Sdc-1 as a signaling co-receptor, we hypothesized that loss of Sdc-1 may regulate HPSE expression." (PMID 32477959, 2020). "This signaling pathway is tightly implicated in colon carcinoma promotion, acting via induction of cell proliferation and inhibition of apoptosis, in agreement with the observed increase in size of Sdc1 KO mice tumors." (PMID 28350804, 2017). "Thus, our in vivo results, mirroring the clinical observations, demonstrate a pro-cancerous net effect of Sdc1 loss in the setting of inflammation-related (colon) cancer." (PMID 28350804, 2017). "An observed overall increase in tumor SDC-1 mRNA was demonstrated by in situ hybridization and protein levels confirmed by immunohistochemistry in tumor-associated stromal cells in breast, lung and colon carcinoma." (PMID 24524203, 2014). "Altogether, our results highlight a previously unknown effect of Sdc1 loss in progression of inflammation-associated cancer and suggest that decreased levels of Sdc1 may serve as an indicator of colon carcinoma progression in the setting of chronic inflammation." (PMID 28350804, 2017). "Previous research has confirmed that SDC1 is crucial for the formation of cancer stem cells in colon cancer, where its depletion was found to enhance colon cancer invasion and cancer stem cell formation by activating integrins and FAK." (PMID 41364407, 2025). "While depletion of syndecan-1 in colon cancer cell line in turn stimulates heparinase expression and retain cells into a stem-like state." (PMID 36906534, 2023). "Previously, we observed that the depletion of Sdc-1 in breast and colon cancer cells increases their migration and invasion capacity, while in endometriotic cells the expression of Sdc-1 promotes their invasive potential." (PMID 35155241, 2022). "In a previous study, we found a decrease in the expression of syndecan-1 and opposite trend for Ets-1 throughout colon carcinoma progression." (PMID 32977498, 2020).
colon carcinoma (continued). "siRNA-depletion of Syndecan-1, and upregulation of heparanase increased the colon cancer stem cell phenotype based on sphere formation assays and phenotypic marker analysis (Side-population, NANOG, KLF4, NOTCH, Wnt, and TCF4 expression)." (PMID 32477959, 2020). "Our results report for the first time the dynamic interplay between Sdc-1 and HPSE in stemness-associated colon cancer via a signaling axis involving early growth response protein 1 (EGR1), FAK, and Wnt." (PMID 32477959, 2020). "In a follow-up study, the group also found that HPSE expression was elevated in syndecan-1 depleted colon cancer cells." (PMID 33330458, 2020). "In colon cancer pathogenesis, complex changes occur in the expression pattern of Syndecan-1 and heparanase during progression from well-differentiated to undifferentiated tumors." (PMID 32477959, 2020). "Here we investigated the regulatory and functional interplay of Syndecan-1 and heparanase employing siRNA-mediated silencing and plasmid-based overexpression approaches in the human colon cancer cell line Caco2." (PMID 32477959, 2020). "Surprisingly, a number of cancer models, utilizing Sdc1-KO mice and tumor types other than colon carcinoma, have shown a reduction in tumorigenesis." (PMID 28350804, 2017). "In contrast, ETS-1 and syndecan-1 are inversely correlated in colon carcinoma, pointing toward the cell type specificity of the effect of syndecan-1." (PMID 26420915, 2015). "Consistent with this, the mRNA expression levels of syndecan-1 and -4 are significantly reduced in several cancer cells, including colon carcinoma cells." (PMID 23705906, 2013). "To test our hypothesis, we manipulated Sdc-1 levels via siRNA knockdown in the human colon cancer cell line Caco2." (PMID 32477959, 2020). "Although some previous studies using colon carcinoma cells have described alterations in the transcriptions of syndecan-2 and -4, our previous work on RSCRCs was only able to detect overexpression of syndecan-1 in metastatic tumors." (PMID 29940912, 2018). "Utilizing a mouse model of colitis-related colon carcinoma induced by the carcinogen azoxymethane (AOM), followed by the inflammatory agent dextran sodium sulfate (DSS), we found that Sdc1 deficiency results in increased susceptibility to colitis-associated tumorigenesis." (PMID 28350804, 2017). "Importantly, induction of IL-6 / STAT3 axis was also detected in colonic tumors derived from Sdc1 KO mice." (PMID 28350804, 2017). "Importantly, increased IL-6 expression levels were also detected in colonic tumors induced by AOM-DSS treatment in Sdc1-KO, as compared to wt mice." (PMID 28350804, 2017). "Importantly, increased activation of STAT3 was also demonstrated in AOM-DSS induced colonic tumors derived from Sdc1-KO, as compared to wt mice, as evidenced by a statistically significant increase (p = 0.004) in the number of cells positive for nuclear-localized pSTAT3." (PMID 28350804, 2017). "For example, decreases in syndecan-1 expression have been observed to correlate with epithelial-mesenchymal transitions (EMT) and poorly differentiated phenotypes in colon cancer." (PMID 33330458, 2020). "Accordingly, increased expression of additional STAT3 target genes critically involved in colon cancer progression, i.e., cytokine CCL-2 and the oncogene Myc, was detected in Sdc1-KO tumors (middle, right, 4D)." (PMID 28350804, 2017). "Chitinase-3-like protein 1 (CHI3L1/YKL-40), a glycoprotein secreted by various cancer cells and stromal cells, enhances the synergic effect of syndecan-1 and β3 integrin and activation of FAK/ERK pathway in ECs to promote angiogenesis in breast and colon cancer." (PMID 36906534, 2023). "It is interesting to note that among the top ~50% of SDC1 and among which the top 20% CASP4 high-expressing lung adenocarcinoma and colon cancer patients (out of 503 for lung and 524 for colon, respectively), approximately 20 (lung) and 50 (colon)% of them possess KRAS mutations." (PMID 33452234, 2021).
colon carcinoma (continued). "Notably, a decrease in Sdc-1 and increase in HPSE expression has been observed in several cancers particularly in colon cancer enhancing tumorigenesis, invasion, and metastasis." (PMID 32477959, 2020). "Our findings could form a conceptual framework for establishing novel therapeutic possibilities and recognize the long-term driven functions of Sdc-1 and HPSE in colon cancer." (PMID 32477959, 2020). "As a possible mechanism of chemotherapy resistance in CRC, the authors proposed that shed SDC1 may interact with soluble heparin-binding EGF-like growth factor enhancing the activation of EGFR and downstream signaling, which in turn decreases the chemotherapeutical sensitivity of colon cancer cells." (PMID 36353562, 2022).
lung carcinoma (26 papers, 2012 to 2025). "In lung cancer cells, high SDC1 expression was linked to a prediction of invasiveness but favorable survival after surgery, whereas elevated soluble SDC1 indicated poor clinical outcome." (PMID 40542654, 2025). "In lung cancer patients, high serum levels of shed SDC1 and bFGF were associated with poor prognosis." (PMID 30526845, 2018). "In lung cancer patients, high serum SDC1 and bFGF levels were associated with poor outcomes at the time of diagnosis." (PMID 26293675, 2015). "The association of high serum levels of both SDC1 and bFGF with poor outcome in lung cancer has been reported." (PMID 26293675, 2015). "The overexpression of syndecan-1 in highly metastatic murine lung carcinoma cells enhances pulmonary metastasis when cells are injected intravenously." (PMID 38275815, 2024). "One study examined the level of SDC1 expression and the chemopreventive effect of all-trans retinoic acid in a benzo(α)pyrene-induced lung cancer model in BALB/c mice." (PMID 26293675, 2015). "Additionally, high serum levels of SDC1, measured by ELISA, is an independent, poor-prognostic classifier in lung cancer patients." (PMID 34503301, 2021). "Indeed, syndecan-1 can be used as a biomarker for a lot of tumors, such as lung cancer, hepatocellular carcinoma, and bladder cancer, among others." (PMID 33669066, 2021). "It has been reported that benzo(α)pyrene induces accumulation of shed SDC1 in lung cancer." (PMID 26293675, 2015). "Through q-RT-PCR analysis, we found six genes (DDR1, HSP90B1, SDC1, RPSA, ERGIC3, and LPCAT1) significantly up-regulated and two genes (GPX3 and TIMP3) significantly down-regulated in the lung cancer tissues." (PMID 23374247, 2013). "The interaction between SDC1 and HMMR, the hyaluronan-mediated motility receptor overregulated in lung cancer, is related to tumor cell motility and differentiation, as well as the pathological stage, T classification, lymph node metastasis, and distant metastasis." (PMID 39228892, 2024). "Once SDC1 is shed from the cell surface by ADAM17, the remaining transmembrane C-terminal fragment undergoes intramembrane proteolysis by γ-secretase and is degraded by the proteasome in A549 lung cancer cells." (PMID 34113616, 2021). "Similar cooperation was found by silencing techniques between syndecan-2 and -4 in actin stress fibre formation in lung cancer cell lines P29 and LM66-H11, or between syndecan-1 and syndecan-4 in the migration of dendritic cells after their phospholipid induced maturation." (PMID 22745764, 2012). "In addition, the transmembrane C-terminal fragment does not affect the proliferation of A549 lung cancer cells in the presence of endogenous SDC1." (PMID 34113616, 2021).
lymphoma (25 papers, 2006 to 2025). A malignant (clonal) proliferation of B- lymphocytes or T- lymphocytes which involves the lymph nodes, bone marrow and/or extranodal sites. "Qualitative scoring by IHC on lymphoma tissue arrays showed that FGF2 and SDC1 expression were indeed specific to the HL tumor microenvironment." (PMID 23988031, 2013). "Although FGF2 may not always mediate SDC1 expression in cancers, SDC1 overexpression, at either a tissue or serum level, has been reported for multiple tumor types including solid tumors, lymphomas, and in a number of lymphoproliferative disorders." (PMID 23988031, 2013).
bladder cancer (24 papers, 2012 to 2025). "The loss of transmembrane syndecan-1 expression in tumour cells was related to higher tumour stage and grade, as well as reduced recurrence-free survival in bladder cancer." (PMID 29207682, 2017). "Loss of SDC1 in tumor cells and the simultaneous increase of serum SDC1 levels in high-stage, high-grade bladder cancer cells suggest that SDC1 shedding is associated with bladder cancer cell aggressiveness." (PMID 26293675, 2015). "Simultaneous loss of syndecan-1 expression in tumour cells and its overexpression in high-stage and high-grade bladder cancer patients serum suggest the importance of syndecan-1 in tumour progression; therefore, this molecule could be a new therapeutic target in human urinary bladder cancer." (PMID 29207682, 2017). "Several studies have used MRM to obtain detailed expression profiles of sEV proteins and to identify potential biomarkers such as HSP90 and syndecan-1 in bladder cancer, and annexin A2 and clusterin in Alzheimer's disease." (PMID 36797736, 2023). "LncRNA ZFAS1 has also been reported to regulate cell proliferation, migration and invasion in bladder cancer by targeting miR-193a-3p/SDC1." (PMID 36240130, 2022). "For example, LncRNA ZNFX1-AS1 targets miR-193a-3p/SDC1 to regulate cell proliferation, migration, and invasion of bladder cancer cells." (PMID 35509814, 2022). "Previously we reported that SDC1 levels are lower in controls compared to bladder cancer, but it hold prognostic significance in the high-grade and high stage tumors shed less SDC1 in voided urines than low-grade and low stage tumors." (PMID 33823873, 2021). "Our results provide a basis for further analysis regarding the potential involvement of SDC1 in platinum resistance of bladder cancer." (PMID 33114033, 2020). "The expression of seven of the 10 bladder cancer -associated diagnostic signature (MMP9, MMP10, PAI1, CA9, APOE, SDC1, and ANG) showed a positive association with bladder cancer diagnosis, while IL8 and A1AT showed a negative correlation with cancer diagnosis." (PMID 31905599, 2019). "The overexpression of MMP10 was associated with higher grade disease, while overexpression of MMP10, PAI1, SDC1 and ANG were associated with high stage bladder cancer and CA9 was associated with low stage bladder cancer." (PMID 31905599, 2019). "Particularly, syndecan-1 (CD138), frequently expressed in epithelial cells and some leukocytes, was found to be increased in bladder cancer patients serum and stroma, especially in muscle-invasive cases." (PMID 29207682, 2017). "In this study, we demonstrate that miR-145 in bladder cancer cells down-regulates syndecan-1 expression, inhibits cell proliferation by inducing senescence, and promotes differentiation into glandular, squamous, and neuroendocrine cells." (PMID 26514209, 2015). "In these reports, the tumor stage and grade can change the value of urinary and serum levels of SDC1 as prognostic tools in urinary bladder cancers." (PMID 26293675, 2015). "In this study, we demonstrate for the first time that miR-145 in bladder cancer cells suppresses syndecan-1 and thereby regulates cell proliferation and expression of some markers of differentiation into squamous, glandular, and neuroendocrine cells." (PMID 26514209, 2015). "Relative to control cases, a reduction in SDC1 and overexpression of MMP9, MMP10, SERPINE1, IL8, APOE, SERPINA1, ANG were associated with high stage bladder cancer." (PMID 25387487, 2014). "Finally, SDC1 was enriched in bladder cancer, neuroactive ligand-receptor interaction, nod-like receptor signaling pathway, olfactory transduction, pathogenic Escherichia coli infection, and sphingolipid metabolism." (PMID 40093327, 2025). "Notably, reduction in miR-494 levels results in enhanced SDC-1 shedding and angiogenesis in medulloblastoma cells, while miR-302a and miR-515-5p inhibit ovarian and bladder cancer cell growth correspondingly via the targeting of SDC-1." (PMID 35118073, 2021).
bladder cancer (continued). "Surface expression of syndecan-1 was inversely correlated with tumor stage in primary nonmuscle-invasive bladder cancer, while high stromal syndecan-1 was associated with poor prognosis." (PMID 26420915, 2015). "Syndecan-1 expression has a prognostic value also in bladder cancer." (PMID 26420915, 2015). "Further studies are warranted to define the potential role for SDC-1 in bladder cancer progression." (PMID 24524203, 2014). "Therefore, syndecan-1 and neuropilins may play an important role in the progression of bladder cancer and their altered expression may serve as a biomarker for prognosis." (PMID 29207682, 2017). "However, localization of SDC1 in the membranous or cytoplasmic compartments may correlate with the stage and aggressiveness of urinary bladder cancers." (PMID 26293675, 2015). "Alone urinary SDC-1 may not be a diagnostic biomarker for bladder cancer, but its urinary levels and cellular localization were associated with the differentiation status of patients with bladder tumors." (PMID 24524203, 2014). "For instance, in bladder cancer, the ANGPTL4/SDC1 signaling axis mediates the interaction between tumor cells and plasma cells, leading to poor immune response." (PMID 40493409, 2025). "This study revealed the significant impact of ferroptosis on bladder cancer TME and identified novel ferroptosis-related TME cell subpopulations, ACSL4+CAFs, and important BCa biomarker SDC1." (PMID 39238647, 2024). "Still, high-grade superficial, and deep invasive bladder carcinomas were also characterized by elevated expression of syndecan-1, while low-grade and non-invasive phenotypes do not." (PMID 29207682, 2017). "In contrast, stromal SDC1 as well as serum SDC1 levels were higher in muscle-invasive compared to non-muscle-invasive bladder cancer cells." (PMID 26293675, 2015).